HNF1A (HNF1 homeobox A)
Diseases named in the same sentence as HNF1A in open-access papers (continued):
Sharing a sentence is not in itself a finding about the gene and the disease.
Hyperglycemia (continued). "In 3 patients with GCK-hyperglycemia and in 1 with HNF1A-MD, insulin therapy was discontinued at the follow-up visit." (PMID 41409604, 2025). "The treatment of GCK-hyperglycemia patients before pregnancy significantly differed from that of HNF1A-MD patients." (PMID 41409604, 2025). "Baseline clinical characteristics of pregnancies in the study participants with GCK-hyperglycemia and HNF1A-MD." (PMID 41409604, 2025). "Information from the post-delivery follow-up period was only available for 6 patients with GCK-hyperglycemia and 7 patients with HNF1A-MD." (PMID 41409604, 2025). "Before pregnancy diet therapy predominated in GCK-hyperglycemia (56.0% vs 0%, p<0.001), while insulin therapy was more frequent in HNF1A-MD (67.0% vs. 17.0%, p=0.006)." (PMID 41409604, 2025). "There were 4 (11%) pregnant patients treated with CSII during pregnancy: 2 with GCK-hyperglycemia and 2 with HNF1A-MD." (PMID 41409604, 2025). "Mutations in the HNF1A and HNF4A genes result in pancreatic β-cell dysfunction, which in turn causes hyperglycemia." (PMID 39902162, 2024). "Thyrotoxicosis and hyperglycemia increased hepassocin expression via the HNF-1α pathway, promoting PEPCK expression and leading to gluconeogenesis and hyperglycemia." (PMID 37509575, 2023). "Among 36 patients of Group 1 with a parental history of hyperglycemia, 21 (Cases 1–21) carried a heterozygous causative variant in GCK or HNF1A, with a pick-up rate of 58.3% (21/36) in this subgroup." (PMID 36178555, 2023). "The most common causal variant of HNF1A-MODY, p.(Gly292fs), presents not only with hyperglycaemia and insulin deficiency, but also with increased lipolysis and markedly lower adult BMI." (PMID 34951657, 2022). "Pancreatic β cells from Haster mutant mice consequently showed variegated HNF1A silencing or overexpression, resulting in hyperglycaemia." (PMID 36202974, 2022). "Hnf1a-null mice showed impaired insulin secretion and subsequent hyperglycemia, suggesting that HNF1A was involved in insulin secretion in mouse beta cells." (PMID 35328643, 2022). "Two weeks post STZ, animals transplanted with HNF1A-MODY iPSC R200Q Het (+/R200Q) cells showed rapid progression to hyperglycemia." (PMID 35918471, 2022). "Whole-body knockout Hnf1α mice suffered from hyperglycemia, hypercholesterolemia, and fatty liver, indicating the essential role of HNF1α in liver function and fat metabolism." (PMID 34771521, 2021). "Mild hyperglycemia and the history of the previous HY point toward ABCC8/KCNJ11 or HNF1α/4α mutations, especially in late onset cases." (PMID 32928245, 2020). "Clinical maternal outcomes in the GCK-hyperglycemia and HNF1A-MD groups." (PMID 41409604, 2025). "Clinical perinatal outcomes in subtypes the GCK-hyperglycemia and HNF1A-MD groups." (PMID 41409604, 2025). "Pathogenic variants in the HNF1A and HNF4A genes, encoding transcription factors hepatocyte nuclear factor‐1 alpha and 4 alpha, can lead to a progressive decline in insulin secretion and hyperglycemia." (PMID 41497485, 2025). "Just like HNF1A mutations, the defect location can affect the age of onset and the severity of hyperglycemia but without a definite genotype–phenotype correlation." (PMID 39408828, 2024). "Higher blood glucose levels while on DZX treatment could involve a mechanism similar to the dual phenotypic presentation in the HNF1A/HNF4A mutations, switching from hypoglycemia to hyperglycemia." (PMID 39421536, 2024). "If HNF1α mutation carriers have hyperglycemia during pregnancy, they should not be treated with sulfonylureas and need to be treated with insulin." (PMID 35299962, 2022). "Of the MODY genes described to date, only hepatocyte nuclear factor-4-alpha (HNF4A; MODY1) and hepatocyte nuclear factor-1-alpha (HNF1A; MODY3) mutations may result in a biphasic phenotype of hypoglycemia in early life and hyperglycemia in later life." (PMID 32670997, 2020).
Hyperglycemia (continued). "Three congenital disorders (ventricular septal defect, dilated pelvicalyceal system and hydrocephalus) in the HNF1A-MD group and one complication (prolonged neonatal hypoglycemia) in the GCK-hyperglycemia group were noted." (PMID 41409604, 2025). "Macrosomia, in particular, is more frequently associated with HNF4A-MODY due to its impact on fetal insulin secretion, but has also been occasionally reported in HNF1A-MODY, potentially reflecting unrecognized maternal hyperglycemia." (PMID 41367630, 2025). "In the HNF1A-MD group, there were 2 miscarriages, while in GCK-hyperglycemia group - one case of prolonged neonatal hypoglycemia." (PMID 41409604, 2025). "Sulfonylureas were used in 17% of HNF1A-MD patients and in 6% of GCK-hyperglycemia patients; all of whom were switched to insulin during pregnancy." (PMID 41409604, 2025). "Incidences of miscarriages were limited to 2 cases in HNF1A-MD; 1 case of prolonged neonatal hypoglycemia occurred in GCK-hyperglycemia." (PMID 41409604, 2025). "Clinical presentation of patients with HNF4A MODY is similar to that of patients with HNF1A MODY, namely hyperglycemia appearing in adolescence or early adulthood (before 25 years of age), with gradual deterioration due to progressive beta cell dysfunction." (PMID 39408828, 2024). "We sequenced HNF1A in 27 patients and GCK in seven subjects with asymptomatic mild fasting hyperglycemia." (PMID 31576961, 2020). "In HNF1A MODY, lowered renal threshold for glucose and milder than in type 1 diabetes postprandial hyperglycemia (note the highest HbA1c in type 1 diabetes group) exert opposite effects on 1,5-AG level." (PMID 30778899, 2019). "There was one preterm delivery noted in each of the HNF1A-MD and GCK-hyperglycemia groups." (PMID 41409604, 2025). "Insulin treatment in pregnancy was introduced earlier in the HNF1A-MD group than in the GCK-hyperglycemia group, however, this difference was not statistically significant (7.50 vs. 13.00 week, p=0.640)." (PMID 41409604, 2025). "Miscarriages in the HNF1A-MD group were are most likely related to higher maternal glucose levels at the beginning of pregnancy, while neonatal hypoglycemia is more likely related to maternal hyperinsulinism in patients with GCK-hyperglycemia." (PMID 41409604, 2025). "The clinician should review the prognosis of the condition and potential changes in medical management (e.g., no treatment in GCK- hyperglycemia and sulfonylurea treatment with HNF1A and HNF4A monogenic diabetes." (PMID 37794142, 2023). "Specifically, activities of HNF1A and HNF4A were highly increased in hyperglycemia." (PMID 36285680, 2022). "Remarkably, compound heterozygous Hnf1a+/−;Haster+/− young mice developed severe fasting and fed hyperglycaemia with hypoinsulinaemia, but otherwise did not exhibit extra-pancreatic manifestations observed in homozygous Hnf1a-mutant mice." (PMID 36202974, 2022). "The phenotype of HNF1A-MODY is characterized by mild nonprogressive hyperglycemia, progressive hyperglycemia, and hyperglycemia with extra-pancreatic characteristics." (PMID 35299962, 2022). "In section B, the non-specific hypoglycemic pattern with hypo/hyperglycemia fluctuation points towards the ABCC8/KCJN11 mutation: if not altered, firstly GCK and then HNF1α/4α should be tested." (PMID 32928245, 2020). "Moreover, GCK-hyperglycemia patients received numerically higher total daily dose of insulin in every trimester compared to HNF1A-MD patients, but the differences were not statistically significant." (PMID 41409604, 2025). "There were no incidences of severe hypoglycemia in GCK-hyperglycemia and HNF1A-MD pregnancies." (PMID 41409604, 2025). "Serum levels of apoM were significantly decreased in HNF-1α /MODY3 subjects when compared with control subjects as well as with HNF-4α /MODY1 subjects, indicating that HNF-1α haploinsufficiency rather than hyperglycemia is the primary cause of decreased serum apoM protein concentrations." (PMID 15461812, 2004).
Hyperglycemia (continued). "Although obesity and insulin resistance are not typical findings in HNF1A-MODY, emerging evidence suggests that environmental and metabolic modifiers, such as maternal hyperglycemia during pregnancy or underlying metabolic syndrome, may influence disease expression." (PMID 41367630, 2025). "Retinopathy present in two HNF1A-MD patients; none of the GCK-hyperglycemia patients had diabetic complications." (PMID 41409604, 2025). "Likewise, no pathogenic variant of HNF1A gene has been found, probably because our data collection is focused mainly on absent autoimmunity, not taking into account other MODY criteria, like family history of hyperglycemia before age 25 years among three consecutive generations." (PMID 35769090, 2022).
pancreatic cancer (41 papers, 2012 to 2026). "Mutations in HNF1A (Hepatocyte Nuclear Factor 1A) have previously been identified in hepatoma, colon cancer and endometrial cancer, and HNF1A gene mutations are associated with risk of pancreatic cancer." (PMID 36248850, 2022). "Other alterations with a tumor-inhibitory impact would be inhibition of ADIPOQ, associated with prostate cancer progression risk, and HNF1A/4A, recently proposed as oncogenic in pancreatic cancer." (PMID 34209203, 2021). "In several studies, HNF1A had been linked to resistance to chemical drugs, including colon cancer 24 and pancreatic cancer 8-10." (PMID 34234870, 2021). "The overexpression of FGFR4 in pancreatic cancer is found to be mediated by an intronic enhancer that is activated by HNF1A, and mutations in the HNF1A-binding site reduced the enhancer activity." (PMID 34035238, 2021). "To understand how Hnf1a deficiency promotes pancreatic cancer, we examined the transcriptional programs controlled by Hnf1a in pancreatic exocrine cells." (PMID 32154941, 2020). "The resulting disruption of the HNF-4α/HNF-1α pathway is also linked to hepatocellular carcinoma metastasis and enhanced apoptosis in pancreatic cancer cells." (PMID 33371430, 2020). "Relatedly, genome-wide association study (GWAS) data has linked HNF1A with the increased risk in pancreatic cancers." (PMID 31685031, 2019). "Experimentally reducing the levels of HNF1A in cells taken from human pancreatic cancers caused the cells to grow less well and form smaller tumors when injected into the pancreases of mice." (PMID 30074477, 2018). "Recently, genome-wide association studies have implicated HNF1A as a susceptibility gene for pancreatic cancer." (PMID 25793983, 2015). "Recent genome-wide association studies (GWAS) and post-GWAS analyses have identified chromosome regions containing the ABO, NR5A2, and CLPTM1L-TERT genes, as well as the HNF1A gene, as susceptibility loci for pancreatic cancer." (PMID 23056513, 2012). "Although it is undetermined whether HNF1A mutations lead to disorders in human exocrine cells, genome-wide association studies (GWAS) have revealed an association between HNF1A SNPs and pancreatic cancer." (PMID 35328643, 2022). "To examine the relationship between Hnf1a and Kdm6a deficiency in pancreatic cancer, we generated mice with pancreas‐specific inactivating Kdm6a mutations and oncogenic Kras mutations [Pdx1Cre, Kdm6aLoxP/LoxP, KrasG12D, hereafter referred to as Kdm6apKO;KrasG12D mice]." (PMID 32154941, 2020). "HNF-1A induced expression of MIA2 has also been implicated in pancreatic cancer." (PMID 29156765, 2017). "However, there is yet no information on the expression or mutation status and the potential role of HNF1A in human pancreatic cancer." (PMID 25793983, 2015). "For example, HNF1A was reported to increase chemosensitivity to gemcitabine by targeting ABCB1 in pancreatic cancer cells." (PMID 41583511, 2026). "In pancreatic cancer, HNF1A was shown to transcriptionally activate 53BP1 expression, with its expression negatively correlated with oxaliplatin chemoresistance in pancreatic ductal carcinoma (PDAC) tissues and cell lines." (PMID 41338163, 2025). "Our study is the first one that identifies HNF1A as a pancreatic cancer-specific hypermethylated gene." (PMID 39165427, 2024). "Another example is the developmental transcription factor HNF1A which is highly enriched in pancreatic cancer stem cells and HNF1A overexpression promotes tumor formation and invasiveness." (PMID 38686617, 2024). "A recent study has shown that HNF1A is highly expressed in pancreatic cancer stem cells (PCSCs), suggesting that HFN1A is a potential central regulator of PCSC function." (PMID 35328643, 2022).
pancreatic cancer (continued). "HNF1A was a novel oncogene that regulates the stem cell properties of human pancreatic cancer, and the key role of HNF1A in HCC was yet to be discovered." (PMID 36105485, 2022). "We have examined HNF1A, a homeodomain transcriptional regulator of liver, gut, kidney, and pancreas, which has been proposed as a candidate pancreatic tumor suppressor." (PMID 32154941, 2020). "CCK-8 assays showed that pancreatic cancer cell proliferation was increased in the siHNF1A group, but it was inhibited in the HNF1A-overexpressing group." (PMID 31949497, 2020). "We found that silencing HNF1α reduced the proliferative, migratory, invasive and colony forming capabilities of pancreatic cancer cells, consistent with previous research that has identified it as a novel oncogene in pancreatic cancer." (PMID 33214606, 2020). "Silencing HNF1α reduced the proliferative, migratory, invasive and colony forming capabilities of pancreatic cancer cells." (PMID 33214606, 2020). "The function of PTEN is regulated by HNF1A and finally affects the survival of pancreatic cancer patients." (PMID 33302876, 2020). "As such, HNF1α has been suggested to play a tumor suppressing role, specifically in both liver and pancreatic cancers." (PMID 33214606, 2020). "Taken together, LINC00673 can through suppress miR-504/ HNF1A regulating invasion and migration in pancreatic cancer." (PMID 31949497, 2020). "Recent studies have showed that HNF1A is a novel oncogene that regulates human pancreatic cancer stem cell properties." (PMID 31810492, 2019). "Overall, this study further validates the importance of HNF1A to PDA while providing a novel and critical role for HNF1A in driving pancreatic cancer stem cell properties." (PMID 30074477, 2018). "It has been recently reported that the disruption of nuclear complexes of CTNNB1 and HNF1A suppressed pancreatic tumor growth." (PMID 29515771, 2018). "Based on these data, we postulate a novel pro-oncogenic function for HNF1A through its maintenance of the pancreatic cancer stem cell properties." (PMID 30074477, 2018). "We have further revealed that HNF1A knockdown activates Akt/mTOR signaling pathway in pancreatic cancer cell lines." (PMID 25793983, 2015). "We further elucidated the downstream signaling pathways that HNF1A exerts its tumor suppressor function in pancreatic cancer and found that HNF1A knockdown activated Akt/mTOR signaling pathway." (PMID 25793983, 2015). "To elucidate the molecular mechanisms modulated by HNF1A inactivation in pancreatic cancer cells, we investigated the impact of HNF1A knockdown on AKT/mTOR signaling pathway." (PMID 25793983, 2015). "Another recent study has also shown that overexpression of HNF1A gene in pancreatic cancer cell lines inhibited cell growth, induced G0/G1 arrest and apoptosis." (PMID 25793983, 2015). "In this study, we aim to demonstrate the expression of HNF1A gene in human pancreatic cancer and the impact of HNF1A deregulation on cell proliferation, cell cycle, apoptosis and signaling transduction in pancreatic cancer cells." (PMID 25793983, 2015). "Selective blocking of HNF1A by specific siRNA significantly promoted pancreatic cancer cell proliferation and inhibited apoptosis in vitro." (PMID 25793983, 2015). "Further study is needed to demonstrate which cell cycle regulator modulates the HNF1A siRNA-mediated proliferation in pancreatic cancer cell lines." (PMID 25793983, 2015). "Second, HNF1A knockdown in pancreatic cancer cells lead to increased cell proliferation and reduced apoptosis." (PMID 25793983, 2015). "Selective blocking of HNF1A by specific siRNA conferred a 2-fold higher rate of cell proliferation, 20% increased S phase and G2 phase cells, and 30-40% reduced apoptosis in pancreatic cancer cell lines." (PMID 25793983, 2015). "We further demonstrated that HNF1A knockdown activated Akt and its downstream target, the mammalian target of rapamycin (mTOR) in pancreatic cancer cells." (PMID 25793983, 2015).